IL10 (interleukin 10)
Diseases named in the same sentence as IL10 in open-access papers (continued):
Sharing a sentence is not in itself a finding about the gene and the disease.
colitis (continued). "Obvious hyperemia and inflammatory cells infiltration were found in the colitis control groups accompanied with higher proinflammatory cytokines (IL-6 and TNF-α) and lower anti-inflammatory cytokines (IL-4 and IL-10)." (PMID 29785192, 2018). "The colitis in DKO mice was characterized histologically by diffuse inflammatory cell infiltrates, compared to smaller aggregates of lymphoid cells in IL10−/− mice." (PMID 29849494, 2018). "Further analysis demonstrated that IL‐35 recombinant protein may regulate inflammation through promoting the secretion of IL‐10 and inhibiting the expression of pro‐inflammatory cytokines such as IL‐6, TNF‐α and IL‐17 in acute colitis model." (PMID 29193791, 2018). "Although deleterious in chemical colitis, mast cells may have a different effect in other colitis models that more closely replicate human IBD, for example, the IL10−/− mouse." (PMID 29849494, 2018). "Mice treated with IL-10-producing bifidobacterial strains tended to lose less weight, 93.06 ± 1.02% and 92.5 ± 1.18% for BS42:BESTBL1181:IL-10 and BS42:BESTExp4:IL-10 groups, respectively, compared to the DNBS-PBS control group, (i.e., colitis control)." (PMID 30622516, 2018). "The scavenger receptors CD163 and CD206 as well as the anti-inflammatory cytokine IL-10 were selectively induced in GRflox but not GRlysM mice during DSS-induced colitis." (PMID 29324769, 2018). "As expected, colitis induced by CD4+CD45RBhigh T cells in immune-depleted mice was associated with a significant increase in Th17 genes, IFNG, IL10 as well as S100A8 and S100A9 (data not shown)." (PMID 30405600, 2018). "Only one IL-10−/− mouse spontaneously developed colitis in an age of 10 weeks and was not included in our study." (PMID 30581430, 2018). "Furthermore, it has been reported that the DSS-induced colitis model is characterized by increased serum levels of IL-6, IL-17, and TNF-α and decreased levels of IL-4 and IL-10." (PMID 30393231, 2018). "We show that this was not the case, as IL-10-afforded protection was only observed if IL-10 induction immediately preceded DSS-mediated colitis." (PMID 29545807, 2018). "The authors concluded that the more severe colitis in these mice was driven by increased barrier permeability due to a lack of IL-10 signaling in epithelial cells." (PMID 29922293, 2018). "In this study, we found the upregulation of IL-10 and Tregs after ERC treatment in colitis mice." (PMID 29784012, 2018). "We demonstrate that Alpk1-deficient mice infected with a pathobiont Helicobacter hepaticus (Hh) develop an unusually potent Th1 CD4+ T-cell response and exacerbated colitis in the absence of IL-10 signalling." (PMID 30228258, 2018). "Synthetic DNA oligonucleotides (ODNs) ameliorate colitis whether induced by DSS, hapten, or in the IL10−/− mouse." (PMID 29515999, 2018). "Besides the influence on IL10, these in vivo experiments show a clear effect of oral BI119 administration in preventing T-cell driven murine experimental colitis." (PMID 30405600, 2018). "Upon demonstration of specific IL-10 expression in inflammation related Ly6c+ leukocytes in vivo, we explored the therapeutic potential of IL-10 expression in Ly6c+ leukocytes in vivo in DSS induced colitis mice." (PMID 30374059, 2018). "In the present study, we demonstrated that the maggot protein may ameliorate DSS-induced colitis by maintaining balanced immune responses through suppressing pro-inflammatory cytokines such as TNF-α and up-regulating IL-10 expression in colons and blood." (PMID 30393231, 2018). "Although CD69−Tregs also product IL-10 and TGF-β1 and express immunosuppressive molecule such as ICOS, GITR, and CTLA-4, they failed to attenuate DSS-induced colitis and T-cell transfer-induced colitis." (PMID 30185773, 2018). "In addition, in the chronic TNBS induced colitis, colonic IL-6, TGF-β, and IFN-γ were also significantly increased in the TNBS-treated HSD mice, but IL-10 was decreased in the TNBS-treated HSD mice." (PMID 27926535, 2017).
colitis (continued). "Adoptive transfer of these IL-33-treated, IL-10-producing B cells prevented spontaneous colitis in IL-10−/− mice without affecting Treg frequency." (PMID 28484466, 2017). "In contrast to HD-DCs, adoptive transfer of IL-4 AADCs did not affect the outcome of DNBS-induced colitis as assessed by macroscopic and histopathology damage scores, and did not induce IL-4 or IL-10 in the spleen." (PMID 28094779, 2017). "C57BL/6 IL-10−/− mice orally infected with isolates from patients with colitis had significantly upregulated type 1 and 17 but not type 2 cytokines in the colon coincident with infiltration of phagocytes, T cells, and innate lymphoid cells (ILCs)." (PMID 28789710, 2017). "However, in TNBS-induced ileitis and DSS-induced colitis, GLP-2 treatment downregulated expression of inflammatory cytokines, including IFN-γ, TNF-α, and IL-1β, while the anti-inflammatory cytokine IL-10 was increased." (PMID 29270177, 2017). "The anti-colitis function of IL-10 appears to be a key, because there is no protection against colitis when HD-DCs are transferred into IL-10 knockout mice." (PMID 29163443, 2017). "IL-10 expression was up regulated in MLN of rTsCRT-immunized mice after induction of colitis but not in colon." (PMID 29036211, 2017). "The importance of IL-10 and of macrophages in suppressing the allergic effects has been described in a murine model of ovalbumin-induced allergic airway hyper-reactivity and DSS-induced colitis applying treatment with filarial cystatin." (PMID 29141050, 2017). "In order to demonstrate that the alteration of the miRNAs in IL10−/− was due to the development of colitis rather than an age effect, we analyzed the expression levels of the candidate miRNAs in the sera of WT mice at the same time points." (PMID 28566745, 2017). "For example, interleukin-10 (IL-10) knockout mice grown under germfree conditions do not develop colitis, whereas conventionally raised mice do." (PMID 28904997, 2017). "The adoptive transfer of p85α+/− BMDMs, but not WT BMDMs, significantly improved the severity in WT colitis mice, and this effect was reversed by anti-IL-10 antibody." (PMID 28733636, 2017). "The research has demonstrated that the administration of H. diminuta-pulsed (HD)-DCs can significantly ameliorate the severity and reduce the mortality of DSS-induced colitis, with an enhanced TH2 response and expression of TH2 cytokines such as IL-10, which is produced mainly by CD4+ T cells." (PMID 29163443, 2017). "The use of IL-4Rα−/− HD-DCs highlighted the reciprocity in the regulation of IL-4 and IL-10 production and the inhibition of colitis, since splenocytes from mice given these cells displayed no increase in IL-4 or IL-10." (PMID 28094779, 2017). "Another study reported that intra-gastric administration of L. lactis expressing recombinant IL-10, a cytokine used in clinical trials for treatment of IBD, could successfully prevent colitis in murine models." (PMID 28491143, 2017). "Based on these observations, testing MCC950 in animals with colitis (i.e., DSS, TNBS, or IL-10−/−) would allow a better characterization of the anti-inflammatory effects resulting from selective inhibition of canonical and non-canonical NLRP3 inflammasome activation." (PMID 28179906, 2017). "This oxidative phenotype is not essential for inducing colitis in Il10-/- mice but contributes to colorectal cancer development." (PMID 29254234, 2017). "Furthermore, as observed for IL-10, pro-inflammatory cytokines measured in the colon tissue of DSS-induced colitis mice pretreated with Hsp65-L." (PMID 28194152, 2017). "In support, our very recent study revealed that TLR4 mediated PA induced inflammatory responses in otherwise healthy secondary abiotic IL10−/− mice without colitis." (PMID 29151895, 2017).
colitis (continued). "More recently, in a trinitrobenzene sulfonate rat colitis model, the intravenous injection of MSC-EVs substantially reduced colonic damage and NF-κB activities, accompanied by decreased proinflammatory cytokines and increased IL-10." (PMID 28402942, 2017). "Overall, the miRNA profile of IL10−/− mice treated with the anti-TNFα therapy was intermediate between those of the non-inflamed group (D28) and the colitis group (D98, PBS treated)." (PMID 28566745, 2017). "We found that most of the miRNAs contained within our signature were specific to the colitis of IL10−/− mice, and were not altered in the other models." (PMID 28566745, 2017). "Contrary to WT HD-DCs, IL-10−/− HD-DCs were unable to attenuate the severity of colitis, nor were they able to drive splenic IL-4 or IL-10 in recipients." (PMID 28094779, 2017). "In our in vivo models, neutralization of IL-10 abrogated the protective effect of MS in mice with endotoxin shock or bacteria-induced sepsis and CLP mice as well as in mice with DSS-induced colitis, further confirming the crucial role of IL-10 in the protective effect of MS." (PMID 27405597, 2016). "We have found that AMT-E exerts intestinal anti-inflammatory activity in the colitis by increasing mucus production, inhibiting neutrophil infiltration, down-regulating TNF-α, IL-1β, and IL-10, as well as suppressing COX-2 and iNOS expression in the mouse colon tissue." (PMID 27527191, 2016). "In IL-10−/− mice (not TLR5−/− mice), emulsifier-induced colitis correlated with enrichments in Biophila and Helicobacter, consistent with previous observations in IL-10−/− mice." (PMID 27531998, 2016). "Colonic inflammation represented by proinflammatory cytokines TNF-α and INF-γ, involved in innate immunity, and the anti-inflammatory cytokine IL-10, was not altered in the mild colitis group, compared to the control." (PMID 27957238, 2016). "Additionally, MK2−/− mice are highly resistant to experimental colitis due to reduced IL-6 and TNF-α production, while IL-10 is later critical for taming colitis." (PMID 26998523, 2016). "Second, there is no direct evidence that the increase expression of IL-10 produced by Treg cells is critical for the improvement of DSS-induced colitis." (PMID 27438072, 2016). "It is unclear that IL-10 production was not necessary for Treg-of-B cells to protect against colitis in our study." (PMID 27581189, 2016). "Transfer of IL-10KO-derived, but not DKO-derived, TEPMs prevented the development of colitis in Lcn2/IL-10 DKO mice and these mice exhibited a significantly lower histological score than control mice at 4 weeks of age." (PMID 27734904, 2016). "We compared the development of colitis between IL-10 KO and OPN/IL-10 double KO (DKO) mice." (PMID 26274807, 2015). "Specifically, mice with proximally spread, but not distally contained, colitis have increased IL-1β, IL-6, IL-17, TNFα, and IFNγ combined with decreased IL-10 in the distal colon." (PMID 26121642, 2015). "IL-10 produced by Treg cells is critical for their function as FoxP3+ T cells lacking IL-10 are unable to suppress the development of gastritis and colitis." (PMID 25807464, 2015). "Taken together, these findings indicate that the effect of OPN deficiency on macrophage cytokine production does not contribute to the rapidly deteriorating colitis in OPN/IL-10 KO mice." (PMID 26274807, 2015). "Like for IL-10 recombinant LAB, LL-TGF-β oral treatments were poorly effective against colitis." (PMID 25889561, 2015). "It was also reported in an experimental TNBS-colitis model in SJL/J mice that the transfer of Treg cells prevents the establishment of the disease and that this protective effect is abolished by the administration of anti-IL-10 and/or anti-TGF-β antibodies." (PMID 25853847, 2015). "In animal studies, it was shown that Bacteroides vulgatus induced colitis in HLA/B27-ß2m rats, but not in IL-10−/− mice and even prevented colitis in IL-2−/− mice." (PMID 26635787, 2015).
colitis (continued). "Previous studies have demonstrated that C. butyricum could suppress intestinal immune disorders by regulating IL-10 production, while B. infantis could attenuate inflammation in DSS-induced colitis in rats." (PMID 25802855, 2015). "To elucidate the role of OPN secreted from colonic epithelia in mucosal immune responses, we examined the impact of OPN deficiency on enteric microbiota by comparing the enteric bacterial composition between IL-10 KO and OPN/IL-10 DKO mice at 3 weeks of age, just before the initiation of colitis." (PMID 26274807, 2015). "Circulating IL-10 levels are not affected during the acute phase of DSS-induced colitis, but strongly increase during the chronic phase." (PMID 26353774, 2015). "Therefore, we first deleted OPN in IL-10 KO mice that had increased OPN mRNA expression in the colon from 4 weeks of age, and compared the development of colitis in these mice with that in IL-10 KO mice." (PMID 26274807, 2015). "Specifically, when we blocked in vivo PGE2 using indomethacin, the anticolitic effect of T. crassiceps infection was clearly abrogated, but IL-10 levels still remained elevated, indicating a major role for PGE2 during T. crassiceps-mediated amelioration of colitis." (PMID 26090422, 2015). "Remarkably, oral administration of curli elevated Il10 transcript levels in the intestinal mucosa of mice with hapten-induced colitis, whereas no significant increase was observed in conventional mice." (PMID 26855788, 2015). "Although colonization of wild-type C57BL/6J mice with H. hepaticus does not result in inflammation or disease, H. hepaticus induces colitis in IL10−/− or SCID/Rag2−/− hosts that received naïve CD4+CD45RBhigh T cells." (PMID 25944983, 2015). "Indeed, acute colitis models induced by DSS are characterized by massive epithelial damage and it has been well established that IL-10 gave the best results in chronic colitis models that are immunological driven." (PMID 25889561, 2015). "Also, in our study, oral enoxaparin reduced the levels of a number of mucosal cytokines including IL-1α, IL-1β, IL-10, MIP-1α, MIP-1β, G-CSF, GM-CSF during colitis." (PMID 26218284, 2015). "As a result, colonic mφ from IL-10−/− mice or mice with LysM-mediated deletion of the IL-10R signaling molecule STAT3 display exaggerated pro-inflammatory responses to bacterial products 95,96,109,115, and the animals develop spontaneous colitis 116,117." (PMID 24942685, 2014). "infantis treatment did not have an impact on IL-10 and IL-12, suggesting that the suppressive effects of B.infantis on the development of colitis occur via different pathways other than the IL-10/IL-12 ratio." (PMID 25275569, 2014). "CD8+ T cells from WT and IL-10 KO mice did not induce colitis when transferred to Rag KO recipients and histopathology of the colons from Rag KO mice that received 106 WT or IL-10 KO CD8+ T cells were normal." (PMID 24502291, 2014). "Ex vivo retroviral gene transfer of CD4+ T cells with IL-10 did not have any therapeutic benefit in acute colitis of immunocompetent mice, though it did prevent induction of colitis in a transfer colitis model using immunodeficient mice." (PMID 24712338, 2014). "Injection of IFN-γ-neutralizing mAb into H. hepaticus-infected IL-10−/− mice suggested that IFN-γ is required for disease onset but not for the chronicity of colitis." (PMID 24489792, 2014). "IL-10 appears to have an important role in the pathogenesis of the disease in this model as SCID mice administered both CD4+CD45RBHi and regulatory T cells together with anti-IL-10 receptor antibodies develop colitis." (PMID 24616886, 2014). "Involvement of microbiota in IBD pathogenesis was supported by experiments performed in germ-free animal models since the presence of microbiota was required to trigger intestinal inflammation in various models (IL-10 and IL-12 knock-out mice, chemically DSS- and TNBS-induced colitis)." (PMID 25580435, 2014).
colitis (continued). "To determine whether the genotype of hematopoietic lineages affected colitis, we generated bone marrow chimeric mice for which recipients and donors were WT (CD45.1) and WT, IL10KO, and IL10/Nox1dKO mice (CD45.2), respectively." (PMID 25014110, 2014). "Notably, ERCs attenuated colitis with significantly reduced DAI, decreased levels of intra-colon IL-2 and TNF-α, but increased expressions of IL-4 and IL-10." (PMID 25475342, 2014). "In IL10/Nox1dKO mice, salubrinal preserved eIF2α phosphorylation through inhibition of the regulatory subunit of the protein phosphatase 1 PP1R15A/GADD34 and prevented colitis." (PMID 25014110, 2014). "For example, in immunocompromised mice, B. fragilis can lessen the colitis induced by Helicobacter hepaticus via its production of PSA, which stimulates the anti-inflammatory IL-10 production from CD4+ T cells and the downregulating of proinflammatory IL-10 production in the colonic tissues." (PMID 24900918, 2014). "In experimental models of non-infectious inflammatory diseases, IL-10 knockout mice develop severe colitis, whereas systemic administration of rIL-10 can prevent development of colitis." (PMID 23526993, 2013). "Specifically, treatment of mice with IL-4 or IL-10 resulted in a marked improvement in the histological appearance of the distal colon and suppression of Th1-cell type cytokines, such as IFN-γ, TNF-α and IL-6 in TNBS-induced murine colitis." (PMID 24314293, 2013). "However, the administration of NOD2 ligands to wild-type mice ameliorates colitis symptoms and NOD2 is involved in inducing a tolerogenic environment by up-regulation of IL-10 expression and proliferation of regulatory T cells." (PMID 23882266, 2013). "In the current study, we investigated the effects of IL-4 or/and IL-10 gene therapy against TNBS-induced murine colitis and found that the liposome-mediated combination gene therapy had a significant efficacy in treatment of TNBS-induced murine colitis." (PMID 24314293, 2013). "Mice lacking IL-10 develop severe colitis, demonstrating that IL-10 maintains control over the immune response to the normal bacterial flora in the gut." (PMID 23555256, 2013). "Relative to wildtype mice, realtime RT-PCR indicated that GC-C expression was not changed in adult IL-10−/− mice with active colitis." (PMID 24244444, 2013). "Similarly, IL-10-dependent TH1 self-regulation is essential in restraining the immune response and preventing tissue damage in models of autoimmune disease including colitis, RA, neuritis, SLE, and uveoretinitis." (PMID 23755052, 2013). "LMWH may act on upstream cytokine pathways, reduce the expression of inflammatory cytokines (such as IL-1β and IL-10) and thus alleviate the inflammation reactions in DSS-induced colitis." (PMID 23874391, 2013). "Other experimental models of colitis such as T cell transfer and IL-10−/− colitis do not display overt inflammation when housed in sterile conditions." (PMID 24137160, 2013). "B1 B cells also play a role in protection from colitis, but their protective role is not due to the production of IL-10, instead IgM and IgA are responsible for the protection." (PMID 22969768, 2012). "Of note, we observed reduced frequencies of regulatory T cells in mice with DSS-induced colitis (data not shown) similarly to what was found in IL-10−/− mice." (PMID 22400037, 2012). "Thus, high expression of Ki67 was observed for premalignant mucosa of IL-10−/− animals, while it was low in premalignant stages of AOM/DSS-induced colitis." (PMID 21799775, 2011). "All four non-malignant controls of IL-10−/− colitis presented membranous expression of beta-catenin." (PMID 21799775, 2011). "The decreased Ppara gene expression level in 7-week-old Il10−/− mice suggests that immune cells might have been activated due to increased bacterial invasion and a lack of regulatory mechanisms through Il10 gene deficiency, even though histopathological signs of colitis were not clearly evident yet." (PMID 20671959, 2010).